ID3 (inhibitor of DNA binding 3)
Diseases named in the same sentence as ID3 in open-access papers (continued):
Sharing a sentence is not in itself a finding about the gene and the disease.
leiomyoma (1 paper, 2017). A well-circumscribed benign smooth muscle neoplasm characterized by the presence of spindle cells with cigar-shaped nuclei, interlacing fascicles, and a whorled pattern. "We were also able to confirm that levels of DARC (P < 0.05), SLC2A5 (P < 0.05), ID3 (P < 0.02), LRNF5 (P < 0.01), UGT8 (P = 0.04), ESR1 (P < 0.01), and PGR (P < 0.01) were significantly lower when luteal phase leiomyomas were compared with proliferative phase leiomyomas." (PMID 28637297, 2017).
Listeria monocytogenes infection (1 paper, 2020). "Previous work employing a Listeria monocytogenes infection model to understand the relative contribution of Id2 and Id3 to SLEC vs. MPEC differentiation had supported a role for Id3 in promoting long lived memory cells." (PMID 33117406, 2020).
lobular breast cancer (1 paper, 2020). "Altogether, our comprehensive study of anchorage independence in human ILC cell lines provides mechanistic insights and clinical implications for metastatic dissemination of ILC and implicates ID1 and ID3 as novel drivers and therapeutic targets for lobular breast cancer." (PMID 32661241, 2020).
meningioma (1 paper, 2020). A generally slow growing tumor attached to the dura mater. "Though there were only four normal samples in GSE43290, the efficacy evaluation results still showed that five genes, including AHCYL2 (AUC = 0.729), FGL2 (AUC = 0.782), ID3 (AUC = 0.926), KCNMA1 (AUC = 0.745), and NMNAT2 (AUC = 0.851), could significantly distinguish meningiomas and normal samples." (PMID 32596316, 2020). "What is more, these genes, excluding ID1, ID3, and NMNAT2, were confirmed to be able to differentiate between the recurrence and nonrecurrence forms of meningioma (P < 0.05)." (PMID 32596316, 2020).
metastatic melanoma (1 paper, 2017). A melanoma that has spread from its primary site to another anatomic site. "Finally, the analysis of an online database of metastatic melanoma patient-derived tissues (GEO accession number: GDS3966) confirmed similar inversed tendency between SOX10 and ID3 expression on one hand and between MITF and ID3 expression on the other hand (46 samples and 48 samples respectively)." (PMID 29299138, 2017).
Middle Ear Infection (1 paper, 2021). "This is the first study of the middle ears of Id compound mutant mice, and high incidence of middle ear infection determined by otoscopy and histological analysis of middle ear suggests that Id1/Id3 compound mutant mice are a novel model for human otitis media (OM)." (PMID 34434211, 2021).
myeloproliferative disease (1 paper, 2017). "ID3 contributes in generation of hematopoietic stem and progenitor cells (HSPC) associated with myeloproliferative disease (MPD)." (PMID 28785583, 2017).
Nephropathy (1 paper, 2023). A nonspecific term referring to disease or damage of the kidneys. "It is conceivable, for instance, that both ID1 and ID3 are upregulated as a protective mechanism against diabetic insults, which may delay but eventually fail to prevent the onset of nephropathy." (PMID 37863933, 2023).
oral cancer (1 paper, 2023). "Considering that ID3 expression, which is a target gene of both Smad1/5/9 and p38, was increased by CCN6 combined with BMP2, and that production of CCN6 and BMP2 increased in the cells before EMT, it is suggested that CCN6 combined with BMP2 suppresses EMT of oral cancer cells in primary lesions." (PMID 37590989, 2023).
otitis media (1 paper, 2021). Inflammation of the anatomical structures of the middle ear, which is most often caused by an infectious process. "More studies need to be done to clarify the underlying mechanism of otitis media in Id1/Id3 mutant mice." (PMID 34434211, 2021). "We speculate that Id1/Id3 mutations lead to an impaired immune system, which compromises the ability of the mutant mice to fight against middle ear inflammation, leading to continuous presence of effusion, epithelia hyperplasia and inflammatory cells." (PMID 34434211, 2021). "A total of 41 Id1−/−; Id3+/− mice, 14 Id1+/−; Id3−/− mice and 21 wild-type mice, aged 30 days, were randomly chosen to be screened for otitis media." (PMID 34434211, 2021). "Because of the upregulated expression of Id1 and Id3 in middle ears after the acute episode of pneumococcal otitis media has been resolved, the two genes are presumed to be involved in the development of otitis media." (PMID 34434211, 2021).
ovarian tumours (1 paper, 2001). "Expression of Id3 mRNA was also examined in primary ovarian tumours and was found in only 12/38 (32%) cases." (PMID 11161400, 2001).
pancreatic acinar cell carcinoma (1 paper, 2021). An adenocarcinoma arising from the pancreas. "In summary, the preference of ID3 for HR can also explain that the majority of ID3-deficient pancreatic acinar cell carcinomas were harboring mutational signatures associated with DSB repair defects, mainly resulting from HR deficiencies." (PMID 34718742, 2021). "Furthermore, we previously reported that pancreatic acinar cell carcinoma displayed a loss of ID3 protein." (PMID 34718742, 2021).
pancreatic ductal adenocarcinoma (1 paper, 2023). An infiltrating adenocarcinoma that arises from the epithelial cells of the pancreas. "Many of those genes were related to various kinds of neoplasia progression (Tpx2, Id3, Top2a, Dab2, Mecom, Nrp1107–112), including pancreatic ductal adenocarcinoma, or pancreatitis (Gsn113)." (PMID 37689751, 2023).
periodontitis (1 paper, 2016). An acute or chronic inflammatory process that affects the tissues that surround and support the teeth. "Only CD274 (programed death-ligand 1 with a major role in suppressing the immune system through a signal that inhibits TCR-mediated activation of IL-2 production and T cell proliferation) and ID3 (DNA-binding protein inhibitor ID-3 is a transcription inhibitor) were decreased with periodontitis." (PMID 27486459, 2016).
rectal cancer (1 paper, 2023). A primary or metastatic malignant neoplasm that affects the rectum. "• Positive feedback loop between PPARγ and ID3 enhances the radiosensitivity of rectal cancer cells." (PMID 37170184, 2023). "• Depletion of ID3 enhances radiosensitivity of rectal cancer cells." (PMID 37170184, 2023). "Thus, the expression of ID3 may affect the efficacy of radiotherapy in patients with rectal cancer and could be used as an indicator in individualized radiotherapy." (PMID 37170184, 2023).
renal fibrosis (1 paper, 2024). A final common manifestation of a wide variety of chronic kidney diseases characterized by glomerulosclerosis and tubulointerstitial fibrosis. "The increased expression levels of renal fibrosis-related genes (Grem2, Id3, Fst, Dcn) and renal damage-related genes (Runx1, Vtn, Clo6a2, Tnxb, Itga8, Timp2, Fgfr2, Fgf9) further supported the idea that miPEP31 deficiency exacerbated Ang II-induced kidney inflammation." (PMID 38992718, 2024).
sarcoma (1 paper, 2015). A usually aggressive malignant neoplasm of the soft tissue or bone. "Id3 has been shown to mediate cisplatin-induced apoptosis in sarcoma cells." (PMID 25693514, 2015).
sarcopenia (1 paper, 2018). Progressive decline in muscle mass due to aging which results in decreased functional capacity of muscles. "However, in C/EBPβ-overexpressing cells, C/EBPβ recruitment at all Id3 regulatory regions examined was enriched as compared to pLXSN suggesting that overexpression, which occurs in vivo with sarcopenia and cachexia, can force C/EBPβ onto elements that are not normally occupied." (PMID 30413755, 2018).
schwannoma (1 paper, 2025). A benign, usually encapsulated slow growing tumor composed of Schwann cells. "Other notable ECM-related genes include that we identified in our analysis with less evidence in schwannoma included: ITGA1, POSTN, SPP1, ID3, ADAMTS6." (PMID 40585242, 2025).
seminoma (1 paper, 2015). A radiosensitive malignant germ cell tumor found in the testis (especially undescended), and extragonadal sites (anterior mediastinum and pineal gland). "In CIS, seminomas and ECs, expression of BMP8B, BMPR1A /2, SMAD1 /4 and ID1 /2 was detected, while ID3 expression was restricted to ECs." (PMID 26226633, 2015).
Splenomegaly (1 paper, 2016). Abnormal increased size of the spleen. "The Id3 KO mice that develop splenomegaly show lymphomatous changes consistent with a previous report." (PMID 27128622, 2016).
systemic lupus erythematosus (1 paper, 2022). An autoimmune multi-organ disease typically associated with vasculopathy and autoantibody production. "In systemic lupus erythematosus (SLE) patients, Id3 expression levels were positively correlated with Treg cell frequencies, and subsequently, mice in which Id proteins were overexpressed showed favorable autoimmune responses." (PMID 35983065, 2022).
thyroid tumor (1 paper, 2021). A benign or malignant neoplasm affecting the thyroid gland. "Our study uncovered that the loss of ID3 enhances the metastatic ability of PTC cells, which is consistent with the results from a previous histopathological study that indicates ID3 might reduce the aggressiveness of thyroid tumors." (PMID 34462424, 2021).
tubular adenoma (1 paper, 2023). A usually polypoid neoplasm arising from the glandular epithelium. "GREMLIN1 expression was significantly upregulated, while the inhibitor of DNA binding (ID) proteins ID1, ID2, ID3 and ID4, all major downstream transcription targets of BMP signaling, were found to be significantly downregulated in serrated adenomas compared to tubular adenomas." (PMID 36326956, 2023).
tumor (110 papers, 2007 to 2025). "A comparative analysis of ID1, ID2 and ID3 expression further implicated ID1 as the dominant family member during disease progression with a 10‐fold higher expression in the primary tumour that increased further during metastasis." (PMID 40116596, 2025). "SIRPA blockade restricted the development of liver metastases in Clec4fcreId3f/f mice, and rescued the phagocytosis of tumour cells by Id3-deficient KCs to wild-type levels in vivo and in vitro." (PMID 38326607, 2024). "Blockade of SIRPA rescues the expression of Dectin1/chemokines/cytokines by ID3‐ deficient KCs, thereby restoring the peritumoral anti‐tumor niche mediated by KCs, including the recruitment and activation of CD8+ T and NK cells." (PMID 39220104, 2024). "Despite normal KC numbers and peritumoural location, the percentage of KCs carrying tumour material 2 weeks after intraportal injection of KPC cells was decreased by around half in Id3-deficient mice in comparison to the control." (PMID 38326607, 2024). "This is achieved by upregulating the memory-associated regulatory factor Id3 and improving the anti-tumor activity of T cells and chimeric antigen receptor-expressing T cells." (PMID 35983065, 2022). "Cross comparison of our DEGs to a E2F1 cistrome revealed many E2F1 target genes (E2f7, Rtel1, Myc, Ybx3 and Id3) being downregulated in β1 integrin-deficient tumours, consistent with slow tumour growth phenotype." (PMID 34782719, 2022). "One notable exception is Burkitt’s lymphoma where ID3 is frequently mutated and appears to act as a tumor suppressor, perhaps due to the growth-promoting properties of E proteins in these cells." (PMID 34031428, 2021). "A previous publication from our lab demonstrates a genomic instability in the form of chromosomal gain and loss in ID3-deficient tumor samples." (PMID 34718742, 2021). "The loss of ID3 leads to sensitivity of tumor cells to PARP inhibition, offering new therapeutic opportunities in ID3-deficient tumors." (PMID 34718742, 2021). "This mutation targets the conserved loop region of ID3, which has been shown to demonstrate loss of the tumor suppressor function of ID3 in in vitro functional studies." (PMID 33801781, 2021). "Initial data associating ID1 and ID3 with cancer emerged from studies of xenografts and spontaneous tumors in genetically engineered mouse models, which typically showed decreased tumor growth and impaired angiogenesis in Id1- and/or Id3-deficient backgrounds." (PMID 34031428, 2021). "Resistance to tumor angiogenesis was reported in mice deficient in 1–3 alleles of ID1/ID3 gene knockout combination." (PMID 28785583, 2017). "Because the loss of Id2 specifically suppresses ileal tumor initiation in ApcΔ716 mice, we confirmed the expression patterns of Id2 and other Id-family members (Id1 and Id3) along the proximal-distal axis of the small intestine." (PMID 26163528, 2015). "Loss of function studies in Id+/−/Id3−/− mice demonstrate normal development but impaired tumor angiogenesis and tumor growth." (PMID 24516656, 2014). "ID3 gene encodes a protein DNA-binding protein inhibitor, overexpressed in several carcinomas and reported to be involved in tumour growth, invasiveness, metastasis and angiogenesis." (PMID 21081927, 2011). "It has also been shown that Id1 and Id3 overexpression correlates with loss of CDKN2A expression in different tumours, suggesting that in some settings Id1/3-induced cell proliferation is mediated through the inactivation of the CDKN2A-pRb pathway." (PMID 20842131, 2010). "Moreover, Id3-deficient KCs were normally located outside and around metastatic tumours, similar to the controls." (PMID 38326607, 2024). "ID3 has been found to be strongly associated with the anti-tumor effects of macrophages." (PMID 39256364, 2024).
tumor (continued). "Furthermore, loss- and gain-of-function experiments demonstrate that ID3 is sufficient to confer this potent anti-tumour activity to mouse bone-marrow-derived macrophages and human induced pluripotent stem-cell-derived macrophages." (PMID 38326607, 2024). "Depending on the activating/repressive function of individual transcription factors, IDR-mutated proteins can be both oncogenes (with MYOD1 mutations promoting the dimerization with MYC), or tumor suppressors (with ID3 mutations impairing its repressor activity)." (PMID 33806614, 2021). "ID1 and ID3 associated with the tumor promotion and metastasis." (PMID 28785583, 2017). "Thus, HR deficiency caused by ID3 loss in tumor cells confers sensitivity to PARP inhibition, which might be used in therapeutic approaches." (PMID 34718742, 2021). "Experimental validation demonstrated that ID3 silencing inhibited tumor cell proliferation and induced cell cycle arrest in ES cell lines." (PMID 40607387, 2025). "In a Wnt-driven tumor, knockdown of Id1 and Id3 resulted in significant impairment of in vitro mammosphere generation and tumor initiation." (PMID 41303422, 2025). "Mechanistically, ID3 controls the activatory/inhibitory receptor balance, which, in turn, controls KC activation by tumour cells." (PMID 38326607, 2024). "ID3 is involved in various cellular processes, including apoptosis, angiogenesis, and tumor transformation." (PMID 39256364, 2024). "In conclusion, this study elegantly elucidates that ID3 plays a pivotal role in enhancing the anti‐tumor immune response mediated by KCs through buffering SIRPA transactivation in the liver." (PMID 39220104, 2024). "The findings suggested that the presence of ID3 is essential for the anti‐tumor activity exhibited by adult KCs." (PMID 39220104, 2024). "Numerous researches have shown that ID3 gene is involved in a variety of cellular processes, including cell proliferation, differentiation, apoptosis and tumor transformation." (PMID 38443816, 2024). "In the GEPIA database, it was demonstrated that tumor tissues had higher levels of ID3 and CD52 expression than normal tissues." (PMID 39256364, 2024). "We report that ID3 expression by KCs endows them with the ability to orchestrate a potent anti-tumour response by establishing a peritumoural phagocytic and activated lymphoid effector niche." (PMID 38326607, 2024). "In support, we found that in vitro ectopic lentiviral-mediated expression of mouse Id3 in mouse BMDMs resulted in their ability to phagocytose KPC tumour cells comparable to that of SIRPA blockade or of wild-type mouse KCs." (PMID 38326607, 2024). "Few studies have investigated the role of PLD4 and ID3 in tumor growth and inhibition, especially PDAC." (PMID 37165046, 2023). "To further explore the relationship between ID3 expression and tumor stroma, we analyzed the correlation between ID3 expression and CAFs in two public databases." (PMID 35347134, 2022). "According to recent research, Id3 is correlated with tumor grades in human astrocytes and is downstream of the EGFR/AKT/Smad5 pathway." (PMID 35599595, 2022). "In the present study, two major subsets of tumor cells, ALB + and ID3 + tumor cells were identified in iCCApps." (PMID 35347134, 2022). "Increasing evidence suggests that dysregulation of Id proteins, particularly Id1, Id2, and Id3, is related to advanced tumor grade and a dismal prognosis in a wide range of human cancers." (PMID 35599595, 2022). "By immunostaining, we find that ID3 was predominantly expressed in the nucleus of tumor cells located in the tumor center and were surrounded by rich stromal components." (PMID 35347134, 2022). "ID3 regulates several biological processes, including cell proliferation, senescence, differentiation, apoptosis, angiogenesis, and tumor transformation." (PMID 36510567, 2022). "ID3, RDH10 and EOMES are transcription factors associated with a dysfunctional tumor-infiltrating T cell state." (PMID 36135194, 2022).